EGF (epidermal growth factor)
Diseases named in the same sentence as EGF in open-access papers (continued):
Sharing a sentence is not in itself a finding about the gene and the disease.
breast carcinoma (continued). "In this regard, EGF-induced miR-15b was shown to stimulate the migration of breast cancer cells, through the suppression of the MTSS1 gene." (PMID 35406622, 2022). "We noticed that chromosomes 1 and 19 represent relatively higher fractions of altered genes in both unstimulated and EGF-stimulated breast cancer cells, whereas differentially expressed genes on chromosome 2 were observed only upon EGF stimulation." (PMID 35892586, 2022). "Screening and Identification of EGF as the targets of Methyltransferase-like 3 (METTL3) in breast cancer (BC)." (PMID 35502895, 2022). "Meanwhile, EGF-treated cancer cells have shown to promote glycolysis-derived serine flux particularly in breast cancer cells." (PMID 35122791, 2022). "HER2 is a tyrosine kinase receptor protein, belonging to the epidermal growth factor (EGF) family, and is among the strongest prognostic biomarkers for breast cancer." (PMID 35729608, 2022). "The results showed that knockdown of Kindlin-2 in both BT549 and MDA-MB-453 stunted EGF-induced breast cancer cell cycle progression." (PMID 35595729, 2022). "The EGF secreted by the TAMs activates the EGFR/ STAT3/SOX‐2 paracrine pathway in the breast cancer, resulting in increased SOX‐2 expression, which in turn enhances the CSC phenotype in the tumor cells." (PMID 34914196, 2022). "Subsequently, we identified GEP100 as a guanine-nucleotide exchange factor that activates Arf6 in the acquisition of invasive and metastatic traits of breast cancer cells upon activation of the epidermal growth factor (EGF)receptor pathway." (PMID 36408139, 2022). "Macrophages expressing EGF promote migration and invasiveness of breast carcinoma cells as well as CSF-1 expression by the latter, and cancer cell-derived CSF-1 is able to induce EGF production in macrophages." (PMID 35326399, 2022). "We detected upregulated PKM2 T405/S406 O-GlcNAcylation upon EGF stimulation in breast cancer MCF-7 cells." (PMID 35931120, 2022). "Wang and colleagues looked at the chemotactic behaviour of breast cancer cells (MDA-MB-231) in epidermal growth factor (EGF) gradients." (PMID 36296089, 2022). "The study also revealed that CBD can block the development of breast cancer cells by preventing them from using epidermal growth factor (EGF)." (PMID 36297340, 2022). "Breast cancer (BC) is a highly heterogeneous disease, classified into different categories according to sex steroid and epidermal growth factor (EGF) receptor-expression profiles." (PMID 36428610, 2022). "FNBP1L promotes epidermal growth factor-induced cell migration and invasion in epidermal and breast cancer." (PMID 34722771, 2021). "CCL2 production has been reported to be more inducible in HER2+/ER− breast carcinoma cells compared with HER2+/ER+ cells under EGF/HRG stimulation, and enhanced NF-κB transcription levels were detected in HER2+/ER− breast carcinoma cells." (PMID 34386431, 2021). "Epidermal growth factor (EGF) signaling appears to negatively regulate POPDC1 expression in breast cancer and adenocarcinoma cells." (PMID 34940515, 2021). "During EMT, the expression of several Ca2+ channels and transporters is modulated by transforming growth factor (TGF-β) and epidermal growth factor (EGF) in human breast cancer cells." (PMID 33806911, 2021). "We previously reported that the constitutive degradation of an endosomal small GTPase RhoB by the CUL3/KCTD10 E3 complex functions in EGF-induced Rac1 activation specifically in HER2-positive breast cancer cell lines, among other breast cancer subtypes." (PMID 34187934, 2021). "Accordingly, a previous study conducted in breast cancer has shown that overexpression of ETS1 in the presence of epidermal growth factor (EGF) enhances MMP-9 promoter activity." (PMID 34023818, 2021). "In contrast, 5 min of preincubation with FIPI was mandatory for significantly inhibiting EGF-induced calcium release in MDA-NEO breast cancer cells." (PMID 33832505, 2021).
breast carcinoma (continued). "This study shows that FGFR activation primes EGF‐mediated responses in breast cancer cells whilst inducing EGFR_T693 phosphorylation from the recycling endosomes." (PMID 34086370, 2021). "HER2, DDR1/2, and EGFR are receptor tyrosine kinases which are frequently upregulated in breast cancer and are activated by various ligands e.g., heregulin, collagens, or EGF, respectively." (PMID 33670586, 2021). "Previous studies have shown that in breast cancer cell lines, activation of EGF or IGF-1 pathways can sharply lower the expression of PR." (PMID 34022815, 2021). "In breast cancer the anti-proliferative effects are induced by inhibition of epidermal growth factor (EGF), NF-kB, ERK/Akt and matrix metalloproteinase (MMP) 2 and 9 signaling pathways." (PMID 34064197, 2021). "Although not widely embraced at that time as a regulatory mechanism, the discovery of two cofilin-dependent phases of increased F-actin barbed-end transients in epidermal growth factor (EGF) stimulated breast cancer cells changed this viewpoint." (PMID 34685706, 2021). "miR-223 expression led to reduced epidermal growth factor (EGF) expression which ultimately inhibited breast cancer cell growth and tumor recurrence in vivo." (PMID 33946741, 2021). "The Skp2-SCF E3 ligase was identified to be engaged in EGF-stimulated Akt ubiquitination in breast cancer cells." (PMID 34409101, 2021). "To gain further insight into how FOXO3a suppresses breast cancer metastasis, we examined the effect of FOXO3a on many microenvironmental genes, including TGF-β, TNF-α, EGF, FGF, PDGF, VEGF, and IGF, which have been implicated in promoting metastasis." (PMID 33262463, 2021). "The HER2/neu receptor is an epidermal growth factor (EGF) family transmembrane tyrosine kinase that is amplified and overexpressed in 20%–30% of breast cancers." (PMID 33691110, 2021). "NAV3 is a microtubule-binding protein whose expression is regulated by TP73 and induced by EGF in breast cancer cells." (PMID 34298611, 2021). "Prolactin receptor (PRLR) and epidermal growth factor receptor (EGFR/ERBB) signaling pathways activated by prolactin (PRL) and epidermal growth factor (EGF), have a major role in the mammary gland development and in the etiology of breast cancer, respectively." (PMID 34572912, 2021). "The CB1 expression was tested using immunohistochemistry, and the result showed 14% of tumors in human breast cancer found in tissues stating the epidermal growth factor (EGF) family member." (PMID 34205169, 2021). "In breast cancer cells MDA-MB-468, EMT induced by EGF was linked to an increase in intracellular Ca2+52." (PMID 33500709, 2021). "The epidermal growth factor pathway serves as a primary mediator for breast cancer initiation and progression by encouraging the proliferation of cancer cells and their survival and promoting resistance to conventional therapy." (PMID 34221232, 2021). "We opted for diabetic retinopathy for VEGF, the Matrigel plug assay for FGF-2 and a xenograft breast cancer model for EGF." (PMID 34680238, 2021). "Here, we examine the role of SHP2 in the responses of breast cancer cells to EGF by monitoring phosphoproteome dynamics when SHP2 is allosterically inhibited by SHP099." (PMID 33755016, 2021). "In order to confirm the binding of 6-gingerol to EGF receptor, we treated the breast cancer cells with recombinant human EGF (25 ng/mL) which showed an increase in the expression of phosphorylated EGFR which significantly downregulated by 6-gingerol." (PMID 33925065, 2021). "Other studies have demonstrated a positive role of INPPL1 in EGF-induced Akt activation and cell migration in breast cancer cells." (PMID 33546420, 2021). "EGF has previously been shown to upregulate VGSC expression/activity and to be associated invasiveness in prostate cancer, breast cancer and non-small cell lung cancer." (PMID 34359733, 2021).
breast carcinoma (continued). "EGFR signaling was shown to promote migration, invasion, and chemotaxis towards EGF and metastasis in breast cancer cells." (PMID 33670586, 2021). "One study showed that the free-floating organoids from the breast cancer cell line PMC42 became adherent upon addition of epidermal growth factor (EGF), concomitant with increased expression of the cell-adhesive proteins laminin and fibronectin." (PMID 34066490, 2021). "Excessive clusters of EGFR (100 times more than normal cells) in the extracellular domain of breast cancer cells and a higher binding affinity towards EGF make it a rational target for its ligand." (PMID 33530291, 2021). "These EGF-induced genomic targets of ERα overlapped with genes overexpressed in HER2-positive breast cancers." (PMID 33498407, 2021). "It was suggested that EGF (epidermal growth factor) secreted by TAMs interacts with EGF receptors on breast cancer cells to further activate the STAT3/Sox2 signaling pathway to induce the CSC stemness phenotype." (PMID 34178692, 2021). "High levels of estradiol, BRAFV600E, or epidermal growth factor (EGF), which are associated with breast cancer, melanoma, and non-small cell carcinoma (NSCLC), respectively, were found to regulate PFKFB3 expression." (PMID 33671514, 2021). "Dysregulation of EGFR expression and signaling was previously well documented to contribute to the progression and metastasis of breast cancer while MSANTD2 played a crucial role in decreased epidermal growth factor endocytosis." (PMID 34627275, 2021). "Using an in vivo mammary tumor model, a synergistic interaction related to epidermal growth factor (EGF) and M-CSF stimulation between macrophages and tumor cells during cell migration and intravasation was observed." (PMID 34884995, 2021). "In the HER2+/EGFR+ breast cancer cell lines examined here, EGF by itself already induced high levels of AP-1 protein, but only low levels of invasion related gene expression and subsequent cell invasion." (PMID 32350443, 2020). "Previous immunohistochemistry data have confirmed that EGF is highly expressed in many human malignancies, such as breast cancer and ovarian cancer." (PMID 32379058, 2020). "Akt activity, which is often associated with drug resistances in breast cancer cells, is strongly controlled by the amount of PI3K and PIP2 in both EGF and HRG conditions." (PMID 33036375, 2020). "LINC01089 (also known as LncRNA Inhibiting Metastasis; LIMT) is an EGF regulated lncRNA which is down-regulated in breast cancer tissues and cell lines, especially in aggressive subtypes of breast cancer." (PMID 33128008, 2020). "Previous studies have shown suppression of Src family kinase blocks epidermal growth factor-induced phosphorylation of AKT in T47D breast cancer cells." (PMID 32862200, 2020). "TRPV4 was an important component of the calcium influx phase induced in MDA-MB-468 breast cancer cells by the EMT inducer epidermal growth factor (EGF)." (PMID 33322037, 2020). "An in vitro study with three breast cancer cell lines showed that Epidermal Growth Factor (EGF) stimulated glucose uptake in EGFR-positive T-47D and MDA-MB-468 cells, but not in the weakly EGFR-positive MCF-7 cells." (PMID 31936350, 2020). "Another study demonstrated CBD’s ability to inhibit epidermal growth factor (EGF)-induced proliferation, migration and invasion of breast cancer cells." (PMID 32708138, 2020). "In summary, these result show that in multiple HER2+ and/or EGFR+ breast cancer cell lines EGF selectively enables and/or potentiates activation of a subset of critical TGFβ-SMAD inducible invasion/migration-associated genes." (PMID 32350443, 2020).
breast carcinoma (continued). "Taken together, we propose that CD99 agonist ligands have potential as novel therapeutic drug candidates to suppress human breast carcinoma via inhibition of EGF-mediated EGFR signaling." (PMID 33050232, 2020). "Previously, TRPM7 was found to participate in EMT induced by tension or EGF in breast cancer, and TGF-β in prostate cancer." (PMID 33381038, 2020). "We identified a total of 95 newly synthesized proteins potentially involved in the migration and invasion of MDA-MB-231 breast cancer cells towards EGF." (PMID 32629869, 2020). "In this paper, we present novel mechanistic insight into the pro-oncogenic EGF-TGFβ-p63-AP-1 interplay in breast cancer cells." (PMID 32350443, 2020). "NHERF1 suppressed EGFR phosphorylation and inhibited EGF-induced proliferation/migration in breast cancer cells." (PMID 32164629, 2020). "In breast cancer, Arf1 controls cell proliferation by regulating the retinoblastoma protein and acts as a molecular switch to activate EGF-mediated responses." (PMID 31991585, 2020). "Consistent with our results, it was reported that EGF from macrophage promoted invasion of breast carcinoma cells." (PMID 32286255, 2020). "A recent study support these observations by noting that EGF-mediated MAPK signaling pathway significantly induced NR2F2 expression in human breast cancer cell lines." (PMID 32631390, 2020). "In conclusion, our results demonstrated that inhibition of EGF endocytosis and induction of apoptosis by Rlip depletion are possible mechanisms of anticancer effects in the human breast cancer cell lines MCF7 and MDA-MB-231." (PMID 32498332, 2020). "In breast cancer, the epidermal growth factor (EGF) rapidly attenuates the expression of inhibiting metastasis (lncRNA LIMT) by enhancing histone deacetylation at its promoter region." (PMID 32429086, 2020). "Breast cancer has four molecular subtypes characterized by varied expressions of estrogen (ER), progesterone (PR), and epidermal growth factor (EGF) receptors (HER2)." (PMID 32733438, 2020). "Heparin-based hydrogel was a suitable scaffold for solid-phase epidermal growth factor presentation and to support the formation of breast cancer cell spheroids." (PMID 32091043, 2020). "A parallel study of integrin expression in the PMC42-ET breast cancer cell line induced to undergo EMT with EGF indicated that ITGA2 and ITGB1, and their downstream regulator ILK, appeared to be upregulated." (PMID 33276802, 2020). "STAT3 is important for ANO1 transcription in response to IL-6 in pancreatic acinar cells and in response to EGF in breast cancer cells." (PMID 33250781, 2020). "EGF/IGF-I induced a co-localization of IGF-IR and FAK, which was evident mostly at the cell membranes of MCF-7 breast cancer cell and caused cell adhesion onto fibronectin, a marker of aggressive breast cancer." (PMID 32466334, 2020). "Our approach has added to the consensus that Annexin A2 plays an important role in the progression of breast cancer, suggesting that stimulus to migrate and invade with an EGF chemoattractant actually induces the nascent translation of Annexin A2." (PMID 32629869, 2020). "Our assessment of Ca2+ influx induced by a variety of stimuli demonstrated the differential contribution of TRPV4 to sustained Ca2+ influx induced by the purinergic receptor activator ATP, the PAR2 activator trypsin, and EGF in MDA-MB-468 breast cancer cells." (PMID 33322037, 2020). "The focal CNAs contained several cancer relevant genes, such as the known breast cancer genes EGF, CDKN2A and BAG1 and some were less established including ZAR1 and BMS1." (PMID 33168853, 2020). "In preclinical study of breast cancer, heparin binding EGF, ligand of EGFR, can enhance the adhesion between tumor cells and brain endothelial cells, and help tumor cells penetrate the blood-brain barrier in breast cancer." (PMID 33537237, 2020). "Research has also shown that Cdc42 is integral for EGF (epidermal growth factor)-mediated cell proliferation in breast cancer." (PMID 32992837, 2020).
breast carcinoma (continued). "Some KEGG signaling pathways (IL17, TNF, Chemokines, ErbB) as well as cancer-associated pathways (Proteoglycans in cancer, Pathways in cancer, Bladder cancer, Breast cancer, Basal cell carcinoma) were enriched after 4 h EGF treatment." (PMID 33115415, 2020). "Having determined 50 ng/mL EGF to be an appropriate chemoattractant for our breast cancer cell line, it was selected as the stimulus in transwell migration and invasion assays in our model." (PMID 32629869, 2020). "In this study, we modulated the BM meshwork via two routes, namely, variation of the developmental stage of the acini by duration of cultivation and EGF-induced BM disintegration, to obtain models of the transitional states of the BM in breast cancer onset." (PMID 32961780, 2020). "In animal models, perivascular macrophages contribute to breast cancer intravasation, which was assisted through positive feedback interactions between EGF from TAM and CSF1 from breast cancer cells." (PMID 32726950, 2020). "Via GPER, estrogens trigger an epidermal growth factor (EGF)-autocrine loop that holds significance for breast carcinoma, and potentially other malignancies that arise from epithelial tissue." (PMID 33329395, 2020). "Next, we examined Annexin A2 mRNA expression using RT-qPCR in breast cancer cell lines, under normal, serum starved and EGF stimulated conditions." (PMID 32629869, 2020). "Our study showed that in vitro Rlip deficiency inhibits EGF endocytosis and downstream signaling from WNT5A to ERK and PIK3CA, which are key proteins involved in the oncogenesis and natural history of breast cancer." (PMID 32498332, 2020). "Several growth factor–related breast cancer genes (EGF, IGF1, IGF1R, IGF2, IGFBP3, IL10, TGFB1, and VEGF), including 26 SNPs, were used as simulation data to evaluate existing algorithms and the proposed HTGA." (PMID 32554381, 2020). "LncRNA LIMT was suppressed by epidermal growth factor (EGF) and downregulated in breast cancer and ovarian cancer, and the EGF secreted from TAMs suppressed the levels of LIMT through activation of the EGF-ERK pathway." (PMID 32190702, 2020). "AuNPs loaded with the epidermal growth factor (EGF) and radiolabeled with 111In (111In-EGF-AuNP) were evaluated in vitro using two breast cancer cell lines with different levels of EGFR expression." (PMID 33375074, 2020). "In order to assess the safety and efficacy of using the EGF-conjugated GNPs and the laser irradiation, alone or combined, in breast cancer cell lines, cytotoxicity tests using the MTT assay were conducted." (PMID 33353068, 2020). "DNAJB1 binds to mitogen-inducible gene MIG6, a tumour suppressor, which positively regulates epidermal growth factor signalling, leading to breast cancer development." (PMID 32139710, 2020). "In this study, we determined that PSD-A is capable of inhibiting EGF-induced STAT3 activation in breast cancer cells." (PMID 33013353, 2020). "EGFR signaling pathway also has a crucial role in mammary cancers, and polymorphism in the EGFR ligand, EGF, was found to affect cancer progression." (PMID 32293263, 2020). "Rather, we focused on how EGFR activation (using EGF as stimuli) influences breast cancer cell glucose metabolism." (PMID 31532771, 2019). "Here, we investigated phenotypic state transition dynamics of Epidermal Growth Factor (EGF)-induced EMT in a breast cancer cell line MDA-MB-468." (PMID 31247884, 2019). "Since role of PIK3CA in tumor growth is essential and EGF activates all oncogenes, it refers to the important impact of EGF in breast cancer." (PMID 34466490, 2019).